GAS6 (growth arrest specific 6)
Diseases named in the same sentence as GAS6 in open-access papers (continued):
Sharing a sentence is not in itself a finding about the gene and the disease.
cancer (continued). "•Response to GAS6 and HGF for cell migration differs between cancer cell lines." (PMID 32055714, 2020). "•Cabozantinib inhibits both GAS6-AXL and HGF-MET pathways in cancer cells." (PMID 32055714, 2020). "We found that blockade of Gas6 partially reduces vimentin protein expression in cancer cells, although this decrease was not statistically significant." (PMID 32174917, 2020). "Furthermore, GAS6 activation of AXL has been suggested to play a less dominant role in settings where AXL is overexpressed, such as in cancer." (PMID 31917795, 2020). "Growth arrest-specific protein 6 (Gas6), one of the endogenous ligands of TAM receptors (Tyro3, Axl, and Mertk), is confirmed to have beneficial functions in hemostasis, inflammation, and cancer growth." (PMID 31263416, 2019). "The Gas6–TAM interaction then activates downstream signaling, which produces biological effects such as cell survival, growth, migration, proliferation, inflammation, and cancer growth." (PMID 31263416, 2019). "Finally, we describe recent progress in targeting Gas6/TAM for cancer therapy, which will assist in future experimental design and increase the potential use of Gas6/TAM as a therapeutic target for cancer." (PMID 29386018, 2018). "Finally, whereas the focus of the current study is aimed at anti-cancer therapeutics, the development of TAM/Gas6 interaction inhibitors in this application will be directly relevant to other applications." (PMID 28272423, 2017). "Together, these observations establish that small molecules that bind to the interface between TAM Ig1 domain and Gas6 Lg1 domain can inhibit TAM activation, and support the further development of small molecule Gas6-TAM interaction inhibitors as a novel class of cancer therapeutics." (PMID 28272423, 2017). "In addition, the Gas6/Axl pathway upregulates Slug expression through MAPK, suggesting a positive feedback loop between Slug and Axl during cancer progression." (PMID 27385093, 2016). "In cancer, AXL signaling can be activated by GAS6 in an autocrine or paracrine manner." (PMID 27834845, 2016). "The tendency of prostate metastases to be osteoblastic rather than osteolytic, further builds a more suitable cancer niche to facilitate DTC dormancy through a Gas6/Axl axis." (PMID 25344858, 2014). "Hence, the role of the Gas6/TAM system has been found to be important in injury, repair, inflammation, hemostasis, autoimmune disease, vascular systems, and cancer." (PMID 24572151, 2014). "Another important feature of vascular remodeling is the ability of cells to migrate, and just as Axl mediates EMT and migration in cancer models, it is able to increase migration in VSMCs by interacting with the myosin heavy chain (MHC)-IIB in response to Gas6-stimulated ROS production." (PMID 25344858, 2014). "It is possible that the adhesion-like extra cellular region of the Axl receptor with its ability to mediate homophilic interactions and adhesion can contribute to a more aggressive cancer phenotype in vivo independent of Gas6 stimulation." (PMID 19888345, 2009). "However, there are three cancer-related genes (GRB2, GAS6, MLLT6) found in regions of gain at least five times more frequently than lost that are not kinases." (PMID 16457699, 2005). "They secrete TGF-β, leukemia inhibitory factor (LIF), growth arrest-specific protein 6 (GAS6), fibroblast growth factor 5 (FGF5), growth differentiation factor 15 (GDF15), and hepatocyte growth factor (HGF), which drive the invasive and proliferative behaviors in cancer cells." (PMID 40313969, 2025). "The production of TGFβ, leukaemia inhibitory factor (LIF), growth arrest-specific protein 6 (GAS6), fibroblast growth factor 5 (FGF5), growth differentiation factor 15 (GDF15) and hepatocyte growth factor (HGF) promotes invasive and proliferative behaviour in cancer cells." (PMID 31980749, 2020).
cancer (continued). "Our data indicate that the GAS6-AXL and HGF-MET signal pathways markedly contribute to cancer cell migration and invasion in an independent manner, suggesting that simultaneous inhibition of these two pathways contributes to the anti-cancer effects of cabozantinib." (PMID 32055714, 2020). "MER phosphorylation is dependent on binding of its ligand GAS6 or protein S; however, ligand-activated pMER is often unstable and difficult to detect without pervanadate pretreatment in human cancer cells, impeding the development of a selective MER kinase inhibitor." (PMID 32042425, 2020). "For example, cancer cell quiescence in the lung is mediated by thrombospondin 1 (TSP1) and bone morphogenetic protein 4 (BMP4), whereas in the bone marrow, TSP1, BMP7, transforming growth factor β2 (TGFβ2), and growth arrest-specific 6 (GAS6) induce and maintain quiescence." (PMID 31623163, 2019). "As Gas6 is secreted by various liver cell types in the TME, abundant levels of free Gas6 might be available to bind cognate Axl receptors and to activate Axl signaling for cancer progression." (PMID 30567378, 2018). "Although there is no existing research on Gas6-specific inhibitors, a recent study exploited a novel way of inhibiting Gas6/Axl signalling, which may inspire the development of better cancer therapies." (PMID 29386018, 2018). "CAFs could mediate cancer cell growth, migration and invasion depending on secreting various nutrients (lactate, glutamine) and signaling molecules, such as aspartic acid, hepatocyte growth factor (HGF), VEGF, growth arrest specific protein 6 (GAS6), and exosomes." (PMID 36945005, 2023). "For instance, osteoblasts may secrete CXC chemokine ligand 12 (CXCL12), TGF-β, growth arrest-specific protein 6 (GAS6), osteoprotegerin (OPG), osteopontin (OPN), and leukemia inhibitory factor (LIF), to promote colonization and dormancy of disseminating cancer cells in bone marrow." (PMID 34685686, 2021). "Moreover, the production of TGFβ, leukemia inhibitory factor (LIF), growth arrest-specific protein 6 (GAS6), fibroblast growth factor 5 (FGF5), growth differentiation factor 15 (GDF15), and hepatocyte growth factor (HGF) promotes invasive and proliferative behavior in cancer cells." (PMID 34646829, 2021). "Interestingly, elevated levels of endogenous GAS6 were identified in putative cancer stem cells (CSCs, CD133+/CD44+) compared to non-CSCs (CD133–/CD44–) isolated from PCa/osteoblast cocultures in vitro and in DTCs isolated from the bone marrow 24 hours after intracardiac injection." (PMID 27028863, 2016). "Though not much is known about GAS6 in the context of RON signaling, GAS6/Axl has been studied in several cancers, including the breast and prostate." (PMID 36833444, 2023). "Whilst loss of FAK has been shown to correlate with compensation by its family member Pyk225, cross-regulation of Gas6/Axl with Pyk2 and FAK, but not Src, have been reported previously in cancer cells." (PMID 32499572, 2020). "Growth arrest–specific protein 6 (GAS6)–induced MER phosphorylation is often unstable and difficult to detect without pervanadate pretreatment in human cancer cells, posing a challenge for the development of selective MER kinase inhibitors." (PMID 32042425, 2020). "This study shows that cell migration was induced by GAS6 and HGF in some cancer cell lines but not in others through Boyden chamber assays." (PMID 32055714, 2020). "GAS6-CAR-T cells did not lyse TAM-low ASPC1 and BxPC3 cell lines, suggesting it may spare normal tissues expressing lower AXL relative to cancer tissues." (PMID 37475048, 2023). "In addition, it has been demonstrated that hepatocyte growth factor (HGF) induces AXL phosphorylation, independent of GAS6, and that the Met-AXL-Elmo2-Dock180 complex is critical for HGF-induced migration of cancer cells." (PMID 31694201, 2019).
infection (30 papers, 2007 to 2025). The state of being infected such as from the introduction of a foreign agent such as serum, vaccine, antigenic substance or organism. "Infection then theoretically increases GAS6 which may increase thrombosis risk versus lower levels of GAS6; this could potentially be a target pathway for future study." (PMID 26193668, 2015). "In HEK293AXL/GAS6KD cells, the addition of recombinant GAS6 restored SFTSV infection in a dose-dependent manner, highlighting an essential role of GAS6 in AXL-mediated viral entry." (PMID 40853130, 2025). "Previous studies have revealed that during enveloped viruses’ infection, the Gas6 serum protein acts as a bridge between the envelope PtdSer and the AXL surface receptor." (PMID 41358161, 2025). "Further work with ZIKV found that sequestration of Gas6 by an AXL decoy receptor inhibited infection." (PMID 40062839, 2025). "Infection of mice with RSV induced an M2-like (regulatory) phenotype in AMs that is dependent on an increase in Gas6/Axl (growth arrest-specific protein 6) signaling, typically associated with efferocytosis." (PMID 36829255, 2023). "AXL and GAS6 expressions are upregulated in the gingival epithelium or blood vessels of mice after infection by P. gingivalis, whereas subsequent infections significantly reduce their expression levels." (PMID 34734092, 2021). "Typical plasma concentrations of Gas6 are 10–100 ng/ml, and 10% serum contains a sufficient amount of Gas6 to promote infection, so our highest dose of 1,000 ng/ml is at least 100 times more Gas6 than should be sufficient for infection." (PMID 33133043, 2020). "Conversely, GAS6 negatively regulates the levels of innate and adaptive immune cells recruited to the infection site." (PMID 29967614, 2018). "Understanding the precise role of GAS6 during infection is therefore important in order to prevent or modulate local immunity for better protection." (PMID 29967614, 2018). "TNF-α in the serum of Gas6−/− infected mice were significantly higher than WT, indicating a systemic reaction to the infection." (PMID 29967614, 2018). "This study is aimed at dissecting the mechanisms by which GAS6 engages distinct immunological phases in the oral mucosa upon infection with an oral pathogen." (PMID 29967614, 2018). "Upon infection, both WT and Gas6−/− mice upregulated the expression of the noted molecules; nevertheless, in Gas6−/− mice the expression levels were significantly higher in comparison to WT mice." (PMID 29967614, 2018). "Collectively, these data suggest that GAS6 facilitates DC migration to the LNs following infection, contributing to a rapid development of adaptive immunity." (PMID 29967614, 2018). "While expression of P-selectin, ICAM-1, and VCAM-1 were increased in infected WT mice, the expression of these molecules was unchanged by the infection in Gas6−/− mice." (PMID 29967614, 2018). "Further analysis revealed that GAS6 induces simultaneously both pro- and anti-inflammatory regulatory pathways upon infection." (PMID 29967614, 2018). "By contrast, a reduced expression of both chemokines was detected in Gas6−/− mice 1 and 3 days after infection." (PMID 29967614, 2018). "The main finding of this study is that Gas6 plasma concentration correlates with organ dysfunction, especially that of kidney and liver, and several markers of infection during septic shock." (PMID 17241453, 2007). "Collectively, these suggest that GAS6 in the mucosal epithelium downregulates the induction of pro-inflammatory cytokines following infection, implying that its absence should actually facilitate leukocyte infiltration upon infection with P. gingivalis." (PMID 29967614, 2018). "We next examined whether AXL and GAS6 are expressed on lymphatic endothelial cells (LECs), and if the infection alters their expression pattern." (PMID 29967614, 2018).
infection (continued). "Thus, integrating the overall roles of GAS6 upon infection lead us to conclude that GAS6 acts to mount a swift innate immune response and rapid initiation of adaptive immunity, while simultaneously restraining both types of responses." (PMID 29967614, 2018). "We thus examined whether in Gas6−/− mice the arrival of innate leukocytes to the oral mucosa is prevented after an acute infection by P. gingivalis." (PMID 29967614, 2018). "To further explore how GAS6 impacts the blood vessels in the oral mucosa under acute inflammatory conditions, we quantified in the gingiva the expression of endothelial adhesion molecules that are known to be upregulated upon infection." (PMID 29967614, 2018). "In addition, they showed that lack of fibrinogen, essential for clot formation and entrapment of GAS in vivo, resulted in a faster dissemination upon subcutaneous infection with GAS6." (PMID 28924140, 2017). "Thus, examining the differential affinity displayed by different isolates in binding to the AXL/Gas6 viral entry receptor(s) may help to further elucidate the mechanism by which the contemporary strains elicit increased infection kinetics." (PMID 30572570, 2018). "In addition, the increase in the frequency of APCs together with the reduction in the monocyte population, suggests that monocytes might differentiate into APCs in Gas6−/− mice upon infection." (PMID 29967614, 2018). "After 1.5 h of infection with K. pneumoniae, the cells were incubated for 6 h with DMEM containing 100 μg/mL gentamycin and 1 μg Gas6 recombinant protein to kill extracellular bacteria." (PMID 37289655, 2023). "The Gas6/TAM system is involved in the recognition of apoptotic debris by immune cells and this mechanism has been exploited by viruses for cell entry and infection." (PMID 37630598, 2023). "Finally, we assessed whether Gas6-treated cells displayed an increased metabolism during infection." (PMID 33803290, 2021). "The results showed that the expression levels of GAS6 and AXL decreased after P. gingivalis LPS infection." (PMID 34734092, 2021). "Of note, while GAS6 and AXL are both augmented in the plasma of SARS-CoV-2 positive patients, GAS6 decreased in time in those patients that survived the infection." (PMID 32998369, 2020). "Upon infection, GAS6 as well as AXL were detected in LECs, suggesting that GAS6 increases permeability similar to blood endothelial cells." (PMID 29967614, 2018). "Our previous work also found that GAS6 and its receptor AXL are expressed in arteries of the gingival lamina propria, while repetitive infections with P. gingivalis down-modulate their expression and prevents innate inflammation." (PMID 29967614, 2018). "Gas6 performed better than PCT and CRP, both broadly used to diagnose infection but, because of their poor accuracy in this specific indication, should not be used to predict disease outcome." (PMID 27788141, 2016). "For example, hAxl was recently shown to enhance the infection mediated by the entry proteins of SINV, RRV and Baculovirus in a PS-dependent manner by binding the serum proteins Gas-6 and Protein S, which in turn bind PS displayed on these viruses' membranes." (PMID 23555248, 2013). "We used a class II aav to readily test for infection and to show that infected human synovial tissue-derived MSCs, through the upregulated expression of IDO, TSG6, and GAS6, may attenuate inflammation and favor immune tolerance." (PMID 37958918, 2023). "Overall, our data clearly indicate that ZIKV-infection of HBVP is dependent on AXL and GAS6." (PMID 32357162, 2020). "To assess involvement of Gas6, we infected two genital epithelial cell lines with ZIKV alone, or with ZIKV pre-incubated for 1 h with SEV, and added Gas6 protein back to cultures at the time of infection." (PMID 33133043, 2020).
infection (continued). "In the same study, Gas6 performed better than procalcitonin and C-reactive protein, which are broadly used to diagnose infection, even though Gas6 levels between survivors and nonsurvivors remained constant over time." (PMID 31485279, 2019). "To further explore the lack of adaptive immunity in Gas6−/− mice, we analyzed early immunological events after infection." (PMID 29967614, 2018). "Neutrophils and Gr-1high monocytes but not DCs nor Gr-1low monocytes (data not shown) accumulated in the blood of Gas6−/− mice 1 and 3 days after infection but returned to normal levels 7 days post-infection." (PMID 29967614, 2018). "First, we examined whether the expression of GAS6 and the second TAM ligand, PROS1, in the gingiva is affected by the infection." (PMID 29967614, 2018). "This molecule is known to be involved in P. gingivalis-induced alveolar bone loss and its expression significantly increased in WT but not Gas6−/− mice due to the infection." (PMID 29967614, 2018). "Nevertheless, since we showed above that the absence of GAS6 resulted in increased production of pro-inflammatory molecules, we analyzed changes in circulating leukocytes at various times after infection." (PMID 29967614, 2018). "Surprisingly, unlike neutrophils and monocytes, the frequencies of APCs were not reduced in the gingiva of Gas6−/− mice after infection, and in fact, their level markedly increased in the tissue." (PMID 29967614, 2018). "Furthermore, elevated distribution of PS on the surface of many virus, including HIV, has been thought to function in concert with Gas6 and TAM receptors on the targeted cells to facilitate viral entry and infection effectively." (PMID 29176978, 2017). "No relation between Gas6 and other clinical or biological features (age, sex, source of infection, infecting micro-organism, lactate, leucocyte count, and so on) was observed." (PMID 17241453, 2007). "Gas6 has never shown to be a marker of infection, and neither PCT nor sTREM-1 are thought to be reliable severity markers during septic shock." (PMID 17241453, 2007). "However, adding back high concentrations of Gas6 during infection did not restore high rates of viral binding in the presence of SEV or liposomes." (PMID 33133043, 2020). "Three days after the infection, infiltration of CD45+ leukocytes, particularly neutrophils and monocytes, into the infected gingiva was seen in WT mice but not in Gas6−/− mice." (PMID 29967614, 2018). "GAS6 does not bind SARS-CoV-2 or promote AXL-induced SARS-CoV-2 virus pseudotype infection." (PMID 33420426, 2021).
cardiovascular diseases (10 papers, 2012 to 2025). "Previous studies have explored the associations between genetic variants of Gas6 and various diseases states, including cardiovascular disorders." (PMID 26284522, 2015). "Its common polymorphism Gas6 c.834+7G>A is associated with decreased risk of cardiovascular diseases." (PMID 23209669, 2012). "More longitudinal inspections are required to elucidate the clinical significance of circulating Gas6 levels in the development of metabolic or cardiovascular diseases in human adults." (PMID 24236135, 2013). "The Axl-Gas6 interaction has various effects on cardiovascular disease." (PMID 39684449, 2024). "Importantly, this study serves as a preliminary exploration of the implications of the Gas6/AXL complex, indicating the need for further relevant investigations beyond cardiovascular disorders." (PMID 40933570, 2025). "The biological significance of the coexpression of Gas6 and Axl proteins in the aorta of CABG patients still remains to be clarified, but it may be related to the pathogenesis of advanced cardiovascular disease." (PMID 24236135, 2013).